E2F2 (E2F transcription factor 2)
Diseases named in the same sentence as E2F2 in open-access papers (continued):
Sharing a sentence is not in itself a finding about the gene and the disease.
cancer (continued). "It would be worth determining whether E2F2 is a putative cancer stem cell marker and whether BET protein inhibition could be therapeutic." (PMID 27081696, 2016). "These hypotheses regarding the mechanisms of action of LXR ligands in cancer cells and the role of E2F2 and other E2F family members in mediating their anti-proliferative effects await further testing and investigation." (PMID 23809258, 2013). "Notably, the MYC, E2F2 and CASP8 genes, which are important regulators of the cell cycle and apoptosis and have previously been implicated in HPV-related processes or cancer 31-33, were identified as common trans-interaction sites in both the HiC and 4C datasets." (PMID 40568071, 2025). "The authors argue that this effect could be explained by increased expression of cyclin B and a reduced expression of cyclin D, E2F1, cyclin E, and E2F2 and thus, conclude that QRC reduced the number of viable cancer cells by this mechanism that is associated with apoptosis." (PMID 38398890, 2024). "This review explores the function of E2F2 in cancer progression and both established and emerging therapeutic strategies aiming at targeting this oncogenic pathway, while also providing a strong basis for further research on the biological function and clinical applications of E2F2." (PMID 38807594, 2024). "Some authors were suggested that miRNAs (for example microRNA-let-7a, miR-125b, miR-146b-3p, miR-638, miR-31, miR-218, miR-454-3p and miRNA-936) by targeting E2F2, could be influenced by cancer progression, overall survival of patients and response to radiochemotherapy." (PMID 36551770, 2022). "In addition, multicancer invasiveness signature and stem cell genes were significantly enriched in the E2F2 low expression phenotype, which indicated that E2F2 may play a role in modulating cancer invasion and cancer stem cells in CRC." (PMID 35069909, 2022). "E2F2 and its coexpressed genes may be involved in cell signaling functions and the “neuroactive ligand-receptor interaction” pathway, which in turn are required for cancer initiation and progression of CRC." (PMID 35069909, 2022). "However, the research on the role of E2F2 in cancers is very limited." (PMID 34316028, 2021). "Our lab is currently investigating the detailed functional implication of E2F2, B-Myb and FOXM1-containing complex in transcriptional regulation and cancer development, which is of great scientific importance and biological significance." (PMID 35844795, 2022). "For example, CDKN2A, E2F1, E2F2, and CDK4 were significantly overexpressed in 28, 26, 24, and 15 cancers, respectively." (PMID 35911954, 2022). "We observed that the methylation of SRGs in diverse cancers was found to be highly heterogeneous, and only E2F2 (n = 11) and E2F1 (n = 9) exhibited hypomethylation in most cancers." (PMID 35911954, 2022). "The expression levels of E2F2 in CRC were appraised based on the Tumor Immune Estimate Resource (TIMER), Oncomine, The Cancer Genome Atlas (TCGA), Gene Expression Omnibus (GEO) database." (PMID 35069909, 2022). "Mechanistically, we showed that miR‐34c regulates Notch signaling and other cancer related pathways by targeting multiple genes (CCNE2, E2F2, E2F5, and HDAC1)." (PMID 35509638, 2022). "Meanwhile, the inhibition of FOXM1 repressed the expression of CDK6, CCND1, CDK2, CCNE2, E2F2, and CDC25A to arrest the cell cycle at G2 phase, which blocks the promotion of cancer-cell mitosis." (PMID 34880209, 2021). "E2F1, E2F2 and E2F7 proteins, which were upregulated in most of the cancer types and appear as high centrality nodes in the bipartite graphs, regulate around 224, 93 and 74 high centrality genes, respectively." (PMID 34728699, 2021). "Genes such are GSTA4, GSTO2, KLK3, PGF were down-regulated and E2F2, MMP9, PIM2, VEGFC are up-regulated in all cancer nodules." (PMID 34209090, 2021). "Inactivation of RB1 expression in cancer leads to the deregulated activity of the transcription of E2F1, E2F2, and E2F3." (PMID 32429447, 2020).
cancer (continued). "The results showed that the mRNA levels of E2F1, E2F2, E2F3, E2F5, E2F7 and E2F8 were significantly lower in adjacent tissues compared with those in carcinoma tissues." (PMID 32117628, 2020). "In accordance with the mRNA expression levels obtained from GEPIA, the protein expression of E2F1, E2F2, E2F3, E2F5, E2F7 and E2F8 were significantly higher in carcinoma tissues." (PMID 32117628, 2020). "Analysis from CHAT revealed that BIRC5, E2F2, KIF2C, FOXM1, and MCM5 were mainly involved in sustaining proliferative signaling in cancer development, with npmi values of 0.15, 0.222, 0.168, 0.218, and 0.157, respectively." (PMID 31579605, 2019). "Experimental overexpression of miR-214 in HCC cells leads to suppression of E2F2, CDK3, and CDK6, cell-cycle arrest at the G1–S checkpoint, and disrupted proliferation of the cancer cells." (PMID 26498144, 2016). "A better understanding of the relationship between E2F2 and MYC in various cancer contexts remains for future study." (PMID 27081696, 2016). "Among these genes, it is worth to notice the presence of important cancer genes such as E2F1, E2F2, and RAD51, which combined starvation and crizotinib down-regulated to a higher extent compared to these treatments alone." (PMID 25909220, 2015). "The region contains multiple genes with a known or suspected role in cancer including ARID1A, E2F2, NBPF1, PAX7, RUNX3 and SDHB." (PMID 25420937, 2014). "The subnetwork of hsa-let-7e retrieved from pan-cancer FFLs includes 57 target genes and 12 TFs including many cancer-related genes such as MYB, E2F2 and HAND1." (PMID 24205155, 2013). "However, the effects of E2F2, E2F4, E2F6, and E2F8 on prostate etiology and cancer growth are poorly understood." (PMID 37569304, 2023). "Given the results of our immune infiltration analysis, we propose that E2F1, E2F2, E2F3, and E2F5 may potentially affect the progression of cancer through anticancer immunity." (PMID 35531101, 2022). "Although many studies have described the functions of E2F2, the downstream genes of E2F2 in cancer have not been fully elucidated." (PMID 35075115, 2022). "E2F1 and E2F2 are highly expressed in many cancer types, but their contribution to malignancy is not well understood." (PMID 36230876, 2022). "However, little is known about the effects of E2F2, E2F4, E2F6, and E2F8 on prostate pathogenesis and cancer progression." (PMID 35531101, 2022). "We speculate that miRNA‐126‐3p may target E2F2 and E2F3 to restrain the cell proliferation and cancer progression of LUSC." (PMID 32598517, 2020). "Interestingly, the two hub genes, E2F2 and E2F3, were all involved in these cancer‐related pathways." (PMID 32598517, 2020). "Moreover, with functional experiments, we demonstrated that after inhibition of the miR-31-3p expression in HCT116 cancer cell line, the c-MYC expression considerably decreased, probably through a direct action of this miRNA on E2F2, a negative regulator of the c-MYC expression." (PMID 32164324, 2020). "Current studies indicate that E2F2 and E2F3 may act as vital regulators in several cancers." (PMID 32598517, 2020). "This could be interpreted in two ways: either mutating a single base in the E2F2/NRF-1 binding site is not enough to abolish activity in cancer cells or different transcription factors are operational in neuronal and cancer cells." (PMID 26848772, 2016).
cancer (continued). "To verify whether E2F2 mediates the cancer-promoting effect of NELFE, we restored the expression level of E2F2 through an expression plasmid lacking the E2F2 3’UTR." (PMID 34295816, 2021).
infection (8 papers, 2011 to 2025). The state of being infected such as from the introduction of a foreign agent such as serum, vaccine, antigenic substance or organism. "Conversely, the invasive ability of ACHN was significantly inhibited after infection with the E2F2-packed lentivirus (P < 0.001)." (PMID 26967247, 2016). "To address this question, we individually blocked the expression of E2F1, E2F2 or E2F3 with one of two different siRNAs prior to infection with HCMV or transduction with recombinant adenoviruses, and then scored cells for a host DDR by γH2AX immunostaining." (PMID 21589897, 2011). "The results indicate that the combination of ADIPOR1, CENPO, E2F2, and H2AC17 genes has the potential as characteristic genes for diagnosing and studying the acute phase of SFTS virus (SFTSV) infection." (PMID 37896902, 2023). "Surprisingly, despite the widespread infection with the virus, changes in the transcriptome remained limited to only a few genes: GALR3, EGR1, E2F2, RNY4, DBX2 were found upregulated, and ITM2C was downregulated." (PMID 33490061, 2020). "The overwhelming majority of changed miRNAs were downregulated after infection and infection plus SP-A2 (1A0) protein rescue, and these were predicted to target genes that play a role in cell cycle and growth and proliferation pathways, such as CCND1, CCND2, CDK7, CDKN2A, E2F1, E2F2, E2F3, and MYC." (PMID 35844510, 2022). "E2F2 and E2F3 do not influence the infection-associated DDR or viral replication." (PMID 21589897, 2011).
adenocarcinoma (2 papers, 2017 to 2022). A common cancer characterized by the presence of malignant glandular cells. "Particularly, in adenocarcinomas E2F2 expression correlated with EMT marker vimentin." (PMID 29072692, 2017).
cardiovascular disease (2 papers, 2020 to 2021). "Among the E2F family, the inhibition of E2F2 expression was proven to induce angiogenesis in cardiovascular disease." (PMID 33221435, 2021). "Similar to E2F1, E2F2 is closely related to the function of vascular endothelial cells and cardiomyocytes, and its dysfunction may also be involved in the pathogenesis of various cardiovascular diseases." (PMID 32420356, 2020).
neurodegenerative disease (1 paper, 2018). A disorder of the central nervous system characterized by gradual and progressive loss of neural tissue and neurologic function. "Among the target genes, which are repressed upon BMMF expression are the tumor suppressor genes E2F2 and TXNIP as well as the phospholipase PLA2G6, which is frequently mutated in neurodegenerative diseases." (PMID 29434270, 2018).
E2F2 also shares sentences with these, for which no sentence is quoted: Clear Cell Renal Cell Carcinoma (3 papers); head and neck squamous cell carcinoma (2); malignant glioma (2); meningioma (2); squamous cell lung carcinoma (2); acute respiratory distress syndrome (1); cardiomyopathies (1); cervical squamous cell carcinoma (1); colon polyps (1); colorectal tumor (1); dilated cardiomyopathy (1); Huntington disease (1); hypertrophic cardiomyopathy (1); kidney cancer (1); laryngeal squamous cell carcinoma (1); leukemia (1); liposarcoma (1); multiple endocrine neoplasia (1); myeloid leukemia (1); Non-alcoholic Fatty Liver Disease (1); oral cancer (1); ovarian tumors (1); Papillary Thyroid Carcinoma (1); Pheochromocytoma and Paraganglioma (1); pilocytic astrocytoma (1); prostate (1); pulmonary fibrosis (1); rectum adenocarcinoma (1); Thrombocytopenia (1); thyroid cancer (1).
A further 1 disease shares a sentence with E2F2 in 1 paper.